CHI3L1 (chitinase 3 like 1)
Diseases named in the same sentence as CHI3L1 in open-access papers (continued):
Sharing a sentence is not in itself a finding about the gene and the disease.
liver fibrosis (continued). "As a biological indicator related to inflammation, CHI3L1 is clinically important for the diagnosis and staging of liver fibrosis caused by various factors, especially for the diagnostic value of advanced liver fibrosis, and it can be used to determine the progression of liver fibrosis." (PMID 38962736, 2024). "Furthermore, CHI3L1 may serve as a non-invasive staging marker for liver fibrosis caused by HBV, HCV, and nonalcoholic fatty liver disease or as a tool to predict the response to antiviral therapy in chronic HBV patients." (PMID 37834128, 2023). "Of course, measurement of serum CHI3L1 cannot completely replace liver biopsy, and some patients will still need invasive examination to confirm diagnosis, making the continued development of noninvasive diagnostic methods for liver fibrosis even more necessary." (PMID 35360517, 2022). "Diagnostic performances of CHI3L1, FIB-4, APRI, AAR, NLR and PLR for liver fibrosis in patients with AILDs." (PMID 40352927, 2025). "In CHI3L1 KO mice, liver fibrosis and tumor number and size were significantly reduced, while T cell infiltration and immune activation were enhanced, indicating dual roles of CHI3L1 in fibrosis and carcinogenesis." (PMID 40643503, 2025). "Limited research has investigated the role of CHI3L1 in diagnosing liver fibrosis in autoimmune liver diseases patients." (PMID 40352927, 2025). "Chitinase 3-like protein 1 (CHI3L1) is a marker of liver fibrosis produced mainly by hepatic macrophages." (PMID 40352927, 2025). "The AUROC for serum CHI3L1 in identifying significant liver fibrosis was 0.939 (95% CI: 0.891 - 0.988), which was higher than that of other non - invasive fibrosis scores (APRI, FIB - 4, GPR, AAR, NLP, and PLR)." (PMID 40352927, 2025). "It is also necessary to clarify the factors that affect CHI3L1 when diagnosing and assessing the degree of liver fibrosis." (PMID 40352927, 2025). "In order to explore the potential differences in serum CHI3L1 levels among patients with liver fibrosis of different etiologies, we compared the CHI3L1 levels between patients with autoimmune liver diseases and CHB patients." (PMID 40352927, 2025). "Further studies have shown that among patients with liver fibrosis, serum CHI3L1 levels are higher in patients with AILDs than in those with CHB." (PMID 40352927, 2025). "Numerous studies have demonstrated the efficacy of CHI3L1 in evaluating and dynamically monitoring the extent of liver fibrosis, with current clinical applications." (PMID 40352927, 2025). "CHI3L1 is a useful non-invasive marker for assessing liver fibrosis prior to treatment in patients with CHB and monitoring changes in liver fibrosis during treatment." (PMID 38962736, 2024). "Among them, CHI3L1, a previously reported noninvasive biomarker for stage diagnosis of hepatic fibrosis, was specifically upregulated in the aged Hep and serum." (PMID 37378670, 2024). "Here, we aimed to review research developments regarding serum CHI3L1 in relation to the pathophysiology and diagnosis of liver fibrosis of various etiologies, providing a reference for the diagnosis, treatment, and prognosis of liver diseases." (PMID 38962736, 2024). "At present, there are few studies on the use of CHI3L1 for the diagnosis of liver fibrosis due to HBV/HDV overlapping infections." (PMID 38962736, 2024). "In HBV-related liver diseases, Chi3l1 not only effectively reflects liver fibrosis severity before antiviral therapy but can also be used to monitor changes in liver fibrosis during therapy." (PMID 39769202, 2024). "CHI3L1 is upregulated in many types of cancer and in diseases with chronic inflammation including rheumatoid arthritis, osteoarthritis, liver fibrosis, inflammatory bowel disease, and bacterial sepsis." (PMID 38791588, 2024).
liver fibrosis (continued). "Accumulating evidence has demonstrated that serum Chi3l1 levels tend to increase with the progression of liver fibrosis; thus, Chi3l1 is a noninvasive serum biomarker for diagnosing and staging liver fibrosis." (PMID 39769202, 2024). "In HCV-related liver diseases, Chi3l1 is a promising marker for estimating the degree of liver fibrosis and evaluating the efficacy of IFN therapies." (PMID 39769202, 2024). "In NAFLD, macrophage-derived Chi3l1 levels increase in accordance with the progression of liver fibrosis." (PMID 39769202, 2024). "In conclusion, the value of CHI3L1 expression in assessing significant liver fibrosis in patients with CHB is clearer and superior to currently known non-invasive diagnostic methods, and it serve as a reliable reference for antiviral therapy." (PMID 38962736, 2024). "Non-coding RNAs such as miR-125-3p, miR-342-3p, and linc00963 regulate CHI3L1 through signaling pathways and play a key role in regulating inflammation-driven liver fibrosis." (PMID 38962736, 2024). "Mechanistically, Chi3l1 can exacerbate the progression of liver fibrosis by inhibiting hepatic macrophage apoptosis through the suppression of Fas expression and the activation of Akt signaling." (PMID 39769202, 2024). "In the process of liver fibrosis, CHI3L1 promotes the proliferation and activation of hepatic stellate cells by stimulating the production of COL1A1 and ACTA2." (PMID 38003338, 2023). "Many scholars have already discovered changes in the content of CHI3L1 in liver injury, liver cancer, liver fibrosis, cirrhosis, and other diseases." (PMID 38003338, 2023). "Several reports demonstrated a close correlation between serum levels of CHI3L1 and severity of hepatic fibrosis in NAFLD, viral hepatitis, and ALD." (PMID 37166517, 2023). "In the prediction of serum CHI3L1 for liver fibrosis in this study, we found that the summary sensitivity and specificity of advanced fibrosis (F ≥ 3) were higher than the significant fibrosis (F ≥ 2) and cirrhosis (F4)." (PMID 35360517, 2022). "CHI3L1 is a novel serological marker for the assessment of liver fibrosis compared to the other four traditional serological markers." (PMID 35280860, 2022). "Correspondingly, we observed the good performance of CHI3L1 in diagnosing liver fibrosis through the ideal results of pooled DOR values in our work." (PMID 35360517, 2022). "In this regard, it is worth conducting an updated and more comprehensive meta-analysis to identify the value of serum CHI3L1 level in the assessment of liver fibrosis." (PMID 35360517, 2022). "Based on these supporting evidence, serum CHI3L1 has been assumed to be a useful biomarker for liver fibrosis and prognosis." (PMID 35280860, 2022). "Some studies demonstrated that CHI3L1 is liver-enriched and has better application value in staging liver fibrosis than platelet ratio index (APRI) and fibrosis-4 index (FIB-4)." (PMID 35280860, 2022). "The primary studies were screened strictly according to inclusion and exclusion criteria, and sensitivity, specificity, and other measures of accuracy of serum CHI3L1 for evaluating liver fibrosis were pooled with 95% confidence intervals." (PMID 35360517, 2022). "In summary, measurement of serum CHI3L1 is emerging as a powerful tool for detecting liver fibrosis, especially in advanced fibrosis." (PMID 35360517, 2022). "To avoid selection bias in our study, we conducted a thorough literature review of the performance of CHI3L1 in liver fibrosis diagnosis in worldwide databases." (PMID 35360517, 2022). "The clinical diagnosis of liver fibrosis has been found that the sensitivity of CHI3L1 as an indicator of liver fibrosis was 27% higher than indicators type III procollagen, type IV collagen, laminin, and hyaluronidase and 22% higher than FibroScan." (PMID 35360517, 2022). "Our report showed that the CHI3L1 is a feasible indicator for liver fibrosis diagnosis, especially for the advanced fibrosis." (PMID 35360517, 2022).
liver fibrosis (continued). "For example, Higashiyama et al22 reported that CHI3L1 promotes liver fibrosis by inhibiting apoptosis in hepatic macrophages." (PMID 31916309, 2020). "At the same time, we assessed the ability of CHI3L1 in determining differences in treatment efficacies of liver fibrosis improvement with the DAA treatment and the PR treatment regimens for CHC patients." (PMID 33082884, 2020). "For the untreated cirrhotic patients, liver fibrosis measured as the CHI3L1 level increased approximately 25% in approximately 2 years (96 weeks), while there were no significant changes in the non-LC patients at such intervals." (PMID 33082884, 2020). "Our data confirmed and reinforced the utility of CHI3L1 to be the marker to monitor liver fibrosis among patients with CHC prior to and following treatments." (PMID 33082884, 2020). "So we explored CHI3L1 as a sensitive biomarker to monitor the regression of liver fibrosis after HCV eradication." (PMID 33082884, 2020). "In this paper, we explored using the dynamic changes of CHI3L1 levels to be the serum marker to monitor liver fibrosis changes with high sensitivity in a noninvasive manner before and after treatment for CHC patients." (PMID 33082884, 2020). "For the untreated cirrhotic patients, liver fibrosis measured as the CHI3L1 level increased to 198.26 (264.90) at the week 96 follow-up vs. 158.17 (177.14) at the baseline, which is an approximately 25% increase in approximately 2 years (96 weeks)." (PMID 33082884, 2020). "CHI3L1 was examined to be the marker to monitor liver fibrosis among the CHC cases prior to and following treatments in this study." (PMID 33082884, 2020). "In this investigation, we used CHI3L1 as a surrogate marker to compare dynamic hepatic fibrosis variations following the elimination of HCV among cases receiving sofosbuvir (SOF)-based regimens and pegylated interferon/ribavirin (PR) treatments." (PMID 33082884, 2020). "The purposes of this study were to explore the expression feature of serum CHI3L1 in the different stages of patients infected with HBV and to analyze the diagnostic value of CHI3Ll in liver fibrosis combined with the pathological data of liver biopsy." (PMID 31916309, 2020). "Many lines of evidence indicated the tight relationship between CHI3L1 and HA, which together were considered as noninvasive markers of liver fibrosis." (PMID 30165890, 2018). "We have previously showed that serum CHI3L1 levels increased with stages of liver fibrosis, and is a good biomarker of substantial fibrosis." (PMID 30301907, 2018). "Additionally, CHI3L1 can accurately diagnose early stages of HCV-related liver fibrosis and distinguish between different stages of fibrosis." (PMID 40821115, 2025). "The results of this study indicate that serum CHI3L1 levels are significantly higher in patients with AILDs associated with significant liver fibrosis than in those without significant liver fibrosis." (PMID 40352927, 2025). "Serum CHI3L1 is an effective non-invasive indicator for assessing liver fibrosis in AILDs patients and may vary in different etiologies." (PMID 40352927, 2025). "CHI3L1 could combine with IL-13 receptor α2 (IL13Rα2) to activate hepatic stellate cells, producing collagen and inducing hepatic fibrosis." (PMID 40821115, 2025). "To evaluate the potential of CHI3L1 as a biomarker for hepatic fibrosis in patients with autoimmune hepatitis, we measured liver stiffness values (LSM), serum CHI3L1 levels, as well as other commonly used hepatic fibrosis scores (FIB-4, APRI, AAR, NLR, PLR, GPR)." (PMID 40352927, 2025). "However, few studies have assessed the relationship between CHI3L1 and liver fibrosis in autoimmune liver diseases (AILDs)." (PMID 40352927, 2025). "Recent studies suggest that CHI3L1 plays an essential role in hepatic fibrosis." (PMID 40821115, 2025).
liver fibrosis (continued). "Furthermore, this study also revealed that patients with AILDs and CHB, both exhibiting similar degree of liver fibrosis, often demonstrate elevated serum CHI3L1 levels." (PMID 40352927, 2025). "The cellular origin of CHI3L1 in the injured liver and its specific mechanism of action in hepatic fibrosis remain unclear, and more in-depth studies are needed to determine whether CHI3L1 can indeed be used as a therapeutic target." (PMID 38962736, 2024). "Therefore, it is necessary to further explore CHI3L1 for the diagnosis of liver fibrosis, including large-scale and multicenter studies, multifactor analysis, and the combined application of multiple indicators or methods." (PMID 38304922, 2024). "However, other similar studies have suggested that CHI3L1 levels cannot significantly differentiate early liver fibrosis (meta-analysis of histologic data in viral hepatitis [METAVIR]F0, F1, and F2)." (PMID 38962736, 2024). "In ALD patients, high levels of Chi3l1 can reflect the severity and remodeling of liver fibrosis." (PMID 39769202, 2024). "Similarly, when CHI3L1 is employed as a marker of liver aging, it should be distinguished from the markers of liver fibrosis since it plays a role in liver fibrosis." (PMID 39872390, 2024). "Liver ultrasound, APRI, FIB‐4, and serum CHI3L1 were used to evaluate liver fibrosis." (PMID 38380526, 2024). "In HBeAg-negative patients with CHB, serum CHI3L1 has high diagnostic efficiency in the staging of liver fibrosis, with a sensitivity and specificity of 80.00 and 71.05%, respectively." (PMID 38962736, 2024). "In summary, serum CHI3L1 levels are associated with the severity of fibrosis in CHC and its progression over time, which is clinically important for monitoring the degree of hepatic fibrosis and thus predicting the clinical outcome in patients with an SVR after treatment with DAAs." (PMID 38962736, 2024). "Future studies are required to confirm the role of CHI3L1 in hepatic fibrosis (that is, determine whether CHI3L1 is a co-existing hepatic fibrosis factor or whether it promotes the formation of hepatic fibrosis)." (PMID 38962736, 2024). "CHI3L1 inhibits hepatic macrophage apoptosis by suppressing Fas expression and activating the Akt signaling pathway in an autocrine manner, leading to hepatic macrophage accumulation and activation, which exacerbates liver fibrosis." (PMID 38962736, 2024). "Additionally, significant advances have been made in understanding the pathogenesis of CHI3L1 in liver fibrosis." (PMID 38962736, 2024). "Several studies have revealed that intrahepatic vascular coagulation (IAOC) is a major cause of the onset and progression of liver fibrosis, cirrhosis, and liver cancer, and the inflammatory factor YKL-40 (Chi3l1) is associated with various inflammatory diseases." (PMID 37693903, 2023). "Using serum CHI3L1 content alone as an indicator to predict the degree of fibrosis is feasible, but the level of CHI3L1 in the liver gradually increases with normal aging, which is unrelated to the existence of liver fibrosis disease." (PMID 38003338, 2023). "This indicates the potential of using CHI3L1 to make an early diagnosis of liver fibrosis." (PMID 35360517, 2022). "Studies have indicated that serum CHI3L1 level in patients with liver fibrosis is significantly higher than in healthy controls, and that high levels of CHI3L1 correlate with the severity of fibrosis, suggesting that CHI3L1 plays an important role in liver fibrosis." (PMID 35360517, 2022). "Serum CHI3L1 has been identified as a potential marker of liver fibrosis in recent years, with several studies demonstrating that CHI3L1 serves as the upstream signalling molecule regulating liver fibrosis." (PMID 35360517, 2022). "However, CHI3L1 is not only important in inflammation and cardiovascular disease but also plays a role in liver fibrosis." (PMID 35280860, 2022). "Overall, there was a positive correlation between serum CHI3L1 and hepatic fibrosis." (PMID 35360517, 2022).
liver fibrosis (continued). "Serum chitinase-3-like protein 1 (CHI3L1) is a promising marker for diagnosing liver fibrosis." (PMID 35360517, 2022). "Serum CHI3L1 appears to be an excellent indicator in the diagnosis of the liver fibrosis." (PMID 35360517, 2022). "Chitinase 3-like 1 (CHI3L1) is a novel biomarker to diagnosis of liver fibrosis." (PMID 35280860, 2022). "This includes, among others, hyaluronic acid (HA) and procollagen III N-terminal propeptide (PIIINP), type VI and type XIV collagens, prothrombin, chitinase 3-like protein 1 (CHI3L1), and an enhanced liver fibrosis panel consisting of HA, PIIINP, and tissue inhibitor of metalloproteinases (TIMP1)." (PMID 33669694, 2021). "Moreover, investigations have suggested that Chi3L1 serum levels correlate with tissue injury and the degree of hepatic fibrosis." (PMID 33498326, 2021). "Recent clinical studies suggest that Chi3L1 serum levels may be related to different stages of liver fibrosis." (PMID 33498326, 2021). "For the untreated cirrhotic patients, CHI3L1 levels increased at week 96 follow-up compared with that at the baseline (194.73 (172.46) vs. 89.50 (242.97), P = 0.048), reflecting continued worsening of liver fibrosis." (PMID 33082884, 2020). "As a result, CHI3L1 serves as the signaling molecule in the upstream to regulate liver fibrosis, which may be used to be the prognostic factor for liver fibrosis." (PMID 33082884, 2020). "Fifth, what is the exact function of CHI3L1 in liver fibrosis?" (PMID 32929074, 2020). "Our results indicate that CHI3L1 could serve as a serum biomarker not only for diagnosing liver fibrosis but also for monitoring the process of chronic liver diseases monoinfected with HBV." (PMID 31916309, 2020). "Similarly, Li et al49 confirmed that CHI3L1 could diagnose HBV-induced liver fibrosis and differentiate mild (F0–F1) from significant/advanced fibrosis (F2–F4)." (PMID 40821115, 2025). "Therefore, this study aims to investigate the correlation between CHI3L1 and liver fibrosis in AILDs, compare serum CHI3L1 with other liver fibrosis assessment methods to explore its clinical application value as a non-invasive diagnostic biomarker for liver fibrosis." (PMID 40352927, 2025). "Considering the biological activities of CHI3L1 determined in RA and hepatic fibrosis such as stimulating the growth of fibroblasts, driving macrophage activation and differentiation, and regulating the ECM, it may have a significant impact on the potential pathobiology of both IPF and RA-ILD." (PMID 37662936, 2023). "Therefore, our study used CHI3L1 to evaluate the extent of liver fibrosis in OSA patients." (PMID 35280860, 2022). "Although CHI3L1 appears promising as a serum biomarker in this limited trial and may also provide a mechanistic link to the pathogenesis of liver fibrosis, further testing is needed to validate its use in the routine management of patients with liver fibrosis." (PMID 35280860, 2022). "And by comparing the levels of serum CHI3L1 in AILDs and CHB patients with similar degrees of liver fibrosis, we investigate the patterns of changes in serum CHI3L1 in chronic liver diseases caused by different etiologies." (PMID 40352927, 2025). "One model, comprising CHI3L1, platelet count, and alpha-fetal protein (AFP), effectively detects HBV-related significant liver fibrosis with an AUROC of 0.805 and 0.819 in training and validation groups, respectively." (PMID 40821115, 2025). "The results demonstrated that serum CHI3L1 had the highest AUROC of 0.939 (95% CI 0.891-0.988, p <0.001) for the diagnosis of significant liver fibrosis, outperforming other non-invasive fibrosis scoring indicators." (PMID 40352927, 2025). "Recent studies in China and other countries have found that the expression level of CHI3L1 in the blood can help assess the degree of liver fibrosis, proposing CHI3L as a new marker of liver fibrosis." (PMID 39872390, 2024).